IL15 (interleukin 15)
Diseases named in the same sentence as IL15 in open-access papers (continued):
Sharing a sentence is not in itself a finding about the gene and the disease.
Obesity (73 papers, 2010 to 2026). Accumulation of substantial excess body fat. "We observed that this process inversely correlates with PC1 and influences the expression of pro-inflammatory IL-15, which has been implicated in conditions such as obesity, type 1 diabetes and celiac disease." (PMID 41278623, 2025). "Several studies have reported that reduced IL15 levels are a common risk factor for sarcopenia, obesity, and immunosenescence." (PMID 38892069, 2024). "Interleukin-15 (IL-15) is a proinflammatory cytokine involved in the development of chronic inflammation leading to obesity-associated metabolic syndrome." (PMID 35250857, 2022). "Abnormal expression of IL-15 has been linked to the occurrence and development of obesity and diabetes." (PMID 33557944, 2021). "Currently, it is known that IL-15 inhibition promotes attenuation of atherosclerotic lesions, and this interleukin is involved in inflammation in adipose tissues leading to obesity-associated metabolic syndrome." (PMID 32295185, 2020). "In a genome-wide study of large and rare copy-number variations associated with obesity, a deletion of a region was revealed which included IL-15 and mitochondrial uncoupling protein gene (UPC1)." (PMID 31333506, 2019). "Based on these results, it is plausible to infer IL-15’s involvement in adipose tissue regulation and association with obesity." (PMID 31333506, 2019). "In humans, plasma IL-15 is significantly decreased in obesity and negatively associated with fat mass." (PMID 31736870, 2019). "A number of single nucleotide polymorphisms (SNPs) have been isolated within the human IL-15 gene and studied for associations with obesity and skeletal muscle response to resistance exercise." (PMID 31333506, 2019). "IL-15 induces the expression pro-inflammatory cytokines such as IL-6 and TNFα from macrophages that are implicated in the pathogenesis of obesity-associated metabolic syndrome." (PMID 27684068, 2016). "Nevertheless, other lines of evidence support our contention that IL-15 plays a pathogenic role in obesity." (PMID 27684068, 2016). "Overall, understanding the players involved in IL-15 signaling will give rise to potential therapies for obesity and its associated disorders." (PMID 27738421, 2016). "The aim of this study is to investigate the mechanisms underlying the pro-obesity role of IL-15 in adipose tissues." (PMID 27684068, 2016). "It has been reported that obese rodents and individuals have lower circulating levels of this cytokine and treatment with IL-15 induces weight loss in wildtype C57BL/6 (B6) mice, IL-15−/− mice, and murine models of obesity." (PMID 25517731, 2014). "IL-15-deficient mice become obese despite unaltered food consumption; IL-15 injections reversed both this obesity and diet-induced obesity, lowered glucose levels and increased insulin sensitivity." (PMID 23690769, 2013). "IL-15 deficient mice become obese despite unaltered food consumption; IL-15 injection reversed both this obesity and diet-induced obesity, lowered glucose levels, and increased insulin sensitivity." (PMID 22935594, 2012). "The blocking of IL-15 and IL-6 in humans and mice is associated with obesity." (PMID 39769263, 2024). "However, IL-15, a key cytokine involved in lymphocyte activation and homeostasis, and resistin, an adipocytokine linked to obesity, insulin resistance, and inflammation, have been poorly studied in this regard." (PMID 35330391, 2022). "Finally, recent research highlights the main role of IL-15 in promoting inflammation in adipose tissues, which, in turn, determines chronic low-grade inflammation that is at the basis of obesity-associated metabolic syndrome." (PMID 34095164, 2021).
Obesity (continued). "Together, these findings suggest that IL-15 treatment could result in weight loss and decreased visceral fat, corroborating with the control of the inflammatory state related to obesity." (PMID 29791651, 2018). "Therefore we evaluated the neutralization of IL-15 in our murine model to gain greater insight into the underlying pathways triggering or accelerating PSC in individuals with obesity in order to identify potential novel therapeutic targets." (PMID 29449577, 2018). "We also observed that IL-15 increases tumor volume as a consequence of inflammation and lipid mobilization.Further in vivo studies are needed to have a better understanding given that inflammation, neutrophil infiltration and obesity are risk factors." (PMID 28379958, 2017). "IL-15 also promotes inflammation in adipose tissues that could sustain chronic inflammation leading to obesity-associated metabolic syndrome." (PMID 27684068, 2016). "Women exhibited progressive increases in plasma interleukin (IL)-6 with obesity severity, whereas men with severe obesity demonstrated elevated IL-15 and IL-1rα plasma levels." (PMID 41977491, 2026). "Several studies have suggested that individuals with obesity have higher IL-15 compared to lean individuals." (PMID 40642656, 2025). "IL-15 plays an important role in the regulation of obesity-related metabolic diseases by inducing chronic adipose tissue inflammation." (PMID 40863244, 2025). "Integrating muscle mass assessment with circulating myokine profiling (myostatin, irisin, IL-15) has been proposed as a strategy to identify metabolically vulnerable obesity phenotypes, supported by emerging multi-center clinical evidence." (PMID 41515940, 2025). "Interleukins such as IL-6 and IL-15 represent important modulators of local interactions between skeletal muscle and adipose tissue in obesity and T2DM." (PMID 41002965, 2025). "IL-15 has been reported as a myokine that improves fatty acid utilization, insulin sensitivity, and endurance capacity, and prevents obesity and diabetes." (PMID 38913071, 2024). "IL-15 knockout mice were shown to be protected from diet-induced obesity, fat accumulation in adipocytes, insulin resistance, increase in free fatty acids, and hepatic steatosis." (PMID 38455231, 2024). "IL-15 is defined as a proinflammatory cytokine included in the development of low-grade chronic inflammation present in MetS related to obesity." (PMID 38140309, 2023). "As previously reported, IL-15 is a regulator of obesity related pathological changes, and can modulate insulin sensitivity." (PMID 35250857, 2022). "Collectively, this evidence suggests that increasing IL-15 expression is a candidate intervention to prevent and remediate obesity and T2D." (PMID 35563026, 2022). "Myokines affecting sarcopenic obesity include IL-6, IL-10, IL-15, myostatin, insulin-like growth factor (IGF-1), irisin, FGF-21, and leukemia inhibitory factor (LIF)." (PMID 35250869, 2022). "Decreased IL-15 levels are reported to be a common mechanism for sarcopenia and obesity, while IL-15 levels are temporarily elevated immediately after resistance and aerobics training." (PMID 35250869, 2022). "These events appear to affect myokines that are effective in sarcopenic obesity such as IL-6, IL-10, IL-15, myostatin, insulin-like growth factor (IGF-1), irisin, and fibroblast growth factor-21 (FGF-21)." (PMID 35250869, 2022). "In fact, IL-15 has attracted considerable attention as a potential regulator to prevent and/or treat obesity and metabolic dysfunction." (PMID 35356722, 2022). "IL-15 has the potential to reduce obesity and increase lean mass through the AMPK and Akt pathways, which increase after exercise in humans and rodents." (PMID 35250869, 2022). "IL-15 knock-out has been previously shown to protect against obesity and diet-induced insulin resistance." (PMID 34822426, 2021).
Obesity (continued). "Although there is much controversy regarding the role of IL-15 in obesity, our study strongly suggests it plays a role in weight gain and adipose tissue expansion during DIO." (PMID 34439950, 2021). "More recently, roles for IL-15 in metabolism have been elucidated, specifically in the context of obesity." (PMID 34861815, 2021). "Ablation of OGT, and thus O-GlcNAcylation, in skeletal muscle (mKO) resulted in increased energy expenditure, improved insulin sensitivity, protection against HFD-induced obesity, and dysregulation of muscle interleukin-15 (Il15) expression." (PMID 34326778, 2021). "Among the top 10 significant DEGs, IL15 and SOCS3 were found to be upregulated in obese asthmatics compared with non-obese asthmatics, which have been previously reported as obesity-associated marker genes." (PMID 34576307, 2021). "Adipose tissue in 25-week-old α7−/− mice had significantly higher expression of genes encoding for TNFα, IL-6, F4/80 and IL-15 as well as CXCL1, which are associated with obesity." (PMID 32708537, 2020). "The multivariate regression model incorporating cleaning index, approximal plaque index, receptor 1 for tumor necrosis factor-alpha (TNFα-R1) and interleukin-15 (IL-15) had a high power to predict overweight or obesity (AUC = 0.894)." (PMID 32872648, 2020). "For instance IL-15 with its anti-obesity effect, TGF-β and IL-7 with their immunosuppressive properties are decreased with obesity in BM." (PMID 32477271, 2020). "On the contrary, obesity decreases AT eosinophil numbers leading to reduced insulin sensitivity while an increase in eosinophils in response to IL-15 overexpression improves obesity-induced insulin resistance." (PMID 31130916, 2019). "Interleukin-15 (IL-15) is a myokine with potential to reduce obesity and increase lean mass through induction of metabolic processes." (PMID 28066259, 2016). "Contrarily, other studies have reported increased expression of IL-15 in obesity and its induction by inflammatory cytokines in adipocytes." (PMID 27684068, 2016). "Early during infection (i.e., d3 p.i.), obesity was again associated with reduced production of cytokines IL-13, IL-5, IL-12p70, IFNγ, TNFα, IL6, and IL-1β, as well as IL-28b (IFNλ), IL-17, and IL-15." (PMID 26110868, 2015). "It has been proven that elevated circulating levels of IL15 can reduce body fat significantly and inhibit obesity." (PMID 25946105, 2015). "We posit that increased adipokine and decreased IL-15 levels during aging constitute a common mechanism for sarcopenia, obesity, and immune senescence." (PMID 22935594, 2012). "In the nvA(H1N1)-ARDS group, obesity and lymphocytopenia were more common and IP-10, interleukin (IL)-12, IL-15, tumor necrosis factor (TNF)α, IL-6, IL-8 and IL-9 were significantly increased versus control." (PMID 21062445, 2010). "This study demonstrates that a 16-week combined aerobic and resistance training program can significantly improve body composition and modulate the expression of key myokines—GDF-15, apelin-12, and IL-15—in older women, with differential responses observed based on obesity status." (PMID 40725674, 2025). "Third, diminished muscle quantity and quality in sarcopenic obesity reduces secretion of beneficial myokines including irisin, interleukin-15, and insulin-like growth factor-1, which ordinarily provide cardioprotection through local and systemic signaling mechanisms." (PMID 41463092, 2025). "Furthermore, IL-15 has the potential to inhibit adipocyte differentiation and reverse diet-induced obesity." (PMID 40725674, 2025). "This immuno-metabolic effects of IL-15 suggest it May be a potential therapeutic target for treating obesity." (PMID 39376657, 2024). "Obesity causes low-grade inflammation mostly due to adipocytes and immune cells secreting proinflammatory molecules such astumor necrosis factor receptors 1 and 2, PTX3, and Il15." (PMID 37240630, 2023). "IL-15 can also inhibit fat cell differentiation and reverse dietary obesity." (PMID 35250869, 2022).
Obesity (continued). "Moreover, enrichment of IL-15 protects against HFD-induced obesity and insulin resistance in mice models." (PMID 35563026, 2022). "To test whether OGT action is mediated through IL-15 in the context of obesity, we subjected mDKO mice to 22 weeks of a HFD." (PMID 34326778, 2021). "We hypothesized IL-15 secretion from muscle is a major contributor to the lean mKO phenotype because an oversecretion of IL-15 from skeletal muscle results in a similar protection against HFD-induced obesity and the onset of metabolic disorders." (PMID 34326778, 2021). "In mouse models of obesity, the white adipose volume and weight of mouse were reduced significantly through IL-15 administration or overexpression, while increased obviously in IL-15 knockdown models." (PMID 33557944, 2021). "In mice, a KO of the Il15 gene results in a significantly greater weight gain without altering appetite, whereas IL-15 treatment results in significant weight loss in Il15 KO mice and mice with diet-induced obesity independently from food intake." (PMID 34834553, 2021). "IL-15 and IL-2 have several similar functions and are highly expressed in obesity." (PMID 33526854, 2021). "As in mice, IL15 is reported to be associated with obesity in humans, and negative correlations between circulating IL-15 levels and both total and abdominal fat have been demonstrated." (PMID 34834553, 2021). "Moreover, skeletal muscle myocytes can express and secrete numerous cytokines such as IL-6, IL-15, and other molecules such as irisin and myonectin, whereas most adipokines are pro-inflammatory, regulated by obesity." (PMID 32272881, 2020). "Previous studies have shown that as obesity increases, skeletal muscle loss leads to an increase in inflammatory adipocytes, such as leptin, tumor necrosis factor alpha (TNF-α), and interleukin (IL-6), and reduces concentrations of adiponectin or IL-15." (PMID 31269909, 2019). "Experimental studies showed a significant decrease in the intestinal lipid absorption, which may in part explain the anti-obesity effects of IL-15." (PMID 29791651, 2018). "Obesity exacerbated experimental PSC in part by overproduction of IL-15." (PMID 29449577, 2018). "Consequently, a plethora of evidence supported the envision of IL15 as a myokine with potential to counteract obesity and T2DM." (PMID 30158466, 2018). "Interleukin-15 is produced by cells from both hematopoietic and non-hematopoietic origin and has been linked to obesity and liver disease." (PMID 29449577, 2018). "Indeed, global IL15 Tg mice develop fatal lymphocytic leukaemia, precluding its suitability as a model of the IL15 functions in obesity." (PMID 30158466, 2018). "Whether the proposed IL15 inhibitory role of WAT browning in obesity could turn into a positive effect in the hypermetabolic context of cachexia remains to be elucidated." (PMID 30158466, 2018). "In contrast to our findings, several studies have reported a beneficial role of IL-15 in obesity." (PMID 27684068, 2016). "Contrarily, our findings on IL-15 knockout (KO) mice indicate that IL-15 promotes obesity." (PMID 27684068, 2016). "Our study suggests that IL-15 may be a therapeutic target not only in autoimmune type 1 diabetes, but also in obesity." (PMID 27684068, 2016). "Interleukin-15 (IL-15) is an immunomodulatory cytokine primarily known for its effects on lymphocytes, specifically Natural Killer (NK) cells and CD8+ T cells, and more recently, for its association with obesity and body mass regulation." (PMID 25517731, 2014). "Obesity status of the patients may be involved in increasing IL‐15 expression." (PMID 32406586, 2020). "Therefore, IL-15 may be a feasible therapeutic target for prevention and treatment in obesity and T2D." (PMID 31736870, 2019).
Obesity (continued). "Il15 ablation in mice has been reported to result in a significant increased weight gain independent of appetite; notably, the mice do not display obesity-associated inflammation, characterized as an increase of serum IL-6 and tumor necrosis factor-α concentrations." (PMID 30382157, 2018). "It has been suggested that IL-15 and aberrant leptin secretion with obesity might instigate an adipose-specific NK-cell expansion and activation in response to high-fat diet overfeeding, stimulating NK-cell IFN-γ, TNF-α, and MCP-1 production, negatively impacting whole-body insulin sensitivity." (PMID 29479350, 2018). "The elevated circulating levels of NEFAs in obesity may contribute to increased IL-15 gene expression in adipose tissues as free fatty acids can activate pathogen-sensing systems like Toll-like receptors (TLRs), leading to the production of pro-inflammatory cytokines." (PMID 27684068, 2016). "Similarly, studying the effect of IL-15 treatment on obesity may be confounded by the profound effects of IL-15 in activating the immune system." (PMID 27684068, 2016). "Although diet induced obesity is characterized by specific gut bacterial changes, whether acute IL-15 treatment in obese animals result in its own characteristic bacterial profiles and mediates the improved glucose and insulin responses have yet to be determined." (PMID 25517731, 2014). "Therefore, altered intestinal lipid absorption may in part explain the anti-obesity effects of IL-15." (PMID 22768089, 2012). "Thus, a decreased level of IL-15 in obesity may reduce the anti-tumor immune response." (PMID 40863244, 2025). "As for the case of the adjusted Cox regression (adjustment for age, gender and obesity, obesity was adjusted for age and gender only), the same variables remained significant except GMCSF and IL-15." (PMID 36147602, 2022). "In the crude Cox regression only obesity (HR 3.923, p=0.015), Sa/FiO2 (HR 0.987, p=0.032), GMCSF (HR 1.975, p=0.034), IL-15 (HR 1.252, p=0.023) and zonulin levels (HR 1.106, p=0.001) were found to be significant." (PMID 36147602, 2022). "We found a regulation of IL-6, IL-8, IL-15, IL-18, and FGF21 in plasma by exercise, while obesity status increased IL-13 and decreased IL-8 and SPARC in the circulation." (PMID 32132925, 2020). "In contrast, IL-1β and CCL2 reflect obesity-related inflammatory burden rather than early metabolic changes, while IL-6 and IL-15 did not reflect early metabolic alterations in this study." (PMID 42196825, 2026). "Whereas, obesity and insulin resistance (IR) are typical pathological changes in PCOS, we speculated that IL-15 plays an important role in PCOS." (PMID 35250857, 2022). "This lack of correlation strengthens the independent role of IL-15 on IMT, avoiding the interference of a well-known CAD risk, that is, obesity." (PMID 34095164, 2021). "Overexpression of IL-15 in skeletal muscle also increases energy expenditure, increases expression of muscle oxidative enzymes, and protects mice from HFD induced obesity and insulin resistance; however, activity level and substrate utilization of these mice do not resemble mKO mice." (PMID 34326778, 2021). "To date, a number of studies have shown that myokines, such as interleukin-6 (IL-6), interleukin-15 (IL-15) and brain-derived neurotrophic factor(BDNF), may be potential regulators of many physiological states and metabolic diseases, such as obesity and IR." (PMID 28702069, 2017). "Most of the myokines measured were regulated by acute exercise (FGF21, IL-6, IL-8, IL-15, and IL-18), and some were released at different levels in plasma over the 24 h in the group of women with obesity in comparison to the non-obese group (SPARC, IL-8, and IL-13)." (PMID 32132925, 2020). "Although IL-15 transgenic mice do not become obese, this model may not be suitable for studying the effect of IL-15 on obesity, as they develop fatal lymphocytic leukemia." (PMID 27684068, 2016).